ACVR2B (activin A receptor type 2B)
Diseases named in the same sentence as ACVR2B in open-access papers (continued):
Sharing a sentence is not in itself a finding about the gene and the disease.
tumor (continued). "Interestingly, in the present study, fat wasting was ameliorated in ACVR2B/Fc‐treated tumour mice, suggesting that targeting ACVR2B is sufficient to preserve fat mass along with muscle mass, independent of food consumption." (PMID 33200567, 2020). "Next, we sought to examine whether changes at the molecular level in the heart could mirror the effects on function, especially given that ACVR2B/Fc administration was sufficient to preserve heart function along with LV wall thickness in tumour‐bearing animals." (PMID 33200567, 2020). "In order to study the role of EGF-CFC family molecules in NB tumor sphere formation, the expression levels of CFC1, TDGF1, ACVR2A, ACVR2B, and ACVR1B were measured using a microarray." (PMID 28620148, 2017). "TGFBR3 belongs to the functional process GO:0071559 (the response to transforming growth factor β) along with ACVR2B (the activin receptor type 2B) and the transcription factor ONECUT2 (one cut domain family member 2) involved, respectively, in cell signaling and tumor growth." (PMID 35740429, 2022). "Conversely, ACVR2B/Fc preserved fat mass ( + 238%, P < 0.001), bone mass ( + 124%, P < 0.0001), SKM mass (quadriceps: + 31%, P < 0.0001), size (cross‐sectional area: + 43%, P < 0.0001) and plantarflexion force ( + 28%, P < 0.05) in tumour hosts." (PMID 33200567, 2020). "Although we witnessed blunted reductions when compared with sham animals in genes such as Lipe, Plin1, Pnpla2, and Fasn in tumour mice treated with ACVR2B/Fc compared untreated tumour mice, there were not statistically significant differences between the two tumour groups." (PMID 33200567, 2020). "Moreover, because of the difficulty in estimating tumour burden, based on the absence of changes in overall liver weights or liver tumour area via histological analysis, we can only speculate that administration of ACVR2B/Fc did not exert anti‐tumour effects." (PMID 33200567, 2020).
spondylopathies (1 paper, 2025). "Lastly, participants with the ACVR2B rs144370188 variant are more likely to develop M46 spondylopathies (OR: 9.93, p = 0.0007) and H25 senile cataract (OR: 3.55, p = 0.013)." (PMID 41261143, 2025).
ACVR2B also shares sentences with these, for which no sentence is quoted: sarcopenia (5 papers); Atrophy (3); diabetes (3); Duchenne muscular dystrophy (3); Anorexia (2); fibrodysplasia ossificans progressiva (2); Hepatic steatosis (2); Hyperglycemia (2); injury (2); Insulin resistance (2); melanoma (2); musculoskeletal disorders (2); adenocarcinoma (1); allergic disease (1); amyotrophic lateral sclerosis (1); beta thalassemia (1); Burkitt lymphoma (1); chronic hepatitis B‐ (1); chronic obstructive pulmonary disease (1); Cirrhosis (1); colon cancer (1); epistaxis (1); Gingival bleeding (1); Glucose intolerance (1); Impaired glucose tolerance (1); inclusion body myositis (1); Infertility (1); Lewis lung carcinoma (1); liver cancer (1); myelodysplastic syndrome (1).
A further 17 diseases each share a sentence with ACVR2B in 1 paper.